QPRT (quinolinate phosphoribosyltransferase)
Diseases named in the same sentence as QPRT in open-access papers (continued):
Sharing a sentence is not in itself a finding about the gene and the disease.
cancer (16 papers, 2017 to 2026). A tumor composed of atypical neoplastic, often pleomorphic cells that invade other tissues. "Quinolinic acid phosphoribosyltransferase (QPRT) is a rate-limiting enzyme that encodes the uronic acid pathway, which is involved in cell cycle progression and cancer cell metabolism." (PMID 35251175, 2022). "Therefore, the effects of DCTPP1 and QPRT on DNA function are probably associated with their cancer-promoting effects." (PMID 32716908, 2020). "The cancer cell intrinsic effects of QPRT upregulation have been studied in a variety of cancer types." (PMID 37876966, 2023). "The down-regulation of QPRT in many cancer types helps tumours in one way but is compensated for in another by tumours acquiring most of their NAD+ via the salvage pathway and by altering NAD+ compartmentation between mitochondria and cytosol." (PMID 36286592, 2022). "QPRT is upregulated in cancer cells, and this upregulation is resistant to inhibitors of nicotinamide phosphoribosyltransferase (NAMPT), the rate-limiting enzyme of the NAD + salvage pathway." (PMID 35251175, 2022). "QPRT is also expressed in 4/28 cancers, all in association with expression of TDO2 and FAMID and 1 with IDO, and in other cancer types." (PMID 36286592, 2022). "As DSCAM-AS1 positively regulated both DCTPP1 and QPRT, the DSCAM-AS1 deficiency probably conferred a cancer-inhibitory effect, such as knocking down both DCTPP1 and QPRT." (PMID 32716908, 2020). "Other abnormalities in KYN pathway activity in tissues of RCC patients include lower expression of QPRT and downregulation of KMO and 3-HAAO, although QPRT activity may vary in different types of cancers." (PMID 39337426, 2024). "QPRT was identified as one the most upregulated genes in cancer." (PMID 35681770, 2022). "It, therefore, highlights the need to further investigate the role of QPRT in cancer biology." (PMID 33613454, 2020). "In high-grade gliomas, QPRT induction offers cancer cells the possibility to catabolize quinolinic acid produced by astrocytes into NAD+, thereby sustaining PARP and the associated base excision repair activities, and consequently rendering cancer cells chemoresistant." (PMID 35681770, 2022). "Here, we investigated the molecular mechanism leading to acquired FK866 resistance in two genetically different cancer cell lines, CCRF-CEM T-ALL cells, which are NAPRT-deficient, and MDA MB231 triple-negative breast cancer cells, which, vice versa, express an active NAPRT enzyme but lack QPRT." (PMID 29541451, 2018). "Under QPRT inhibition, NAD+ synthesis is secured by the activation of a salvage pathway, often preferred by cancer cells, in which nicotinamide is converted by nicotinamide phosphoribosyltransferase (NAMPT) into NAD+." (PMID 39337426, 2024). "Nonetheless, the metabolic plasticity of cancer cells generally leads to acquired resistance to NAMPT inhibition, and increased expression or activity of QPRT is a novel resistance mechanism." (PMID 33613454, 2020). "Similarly, QPRT expression has shown great relevance to the migration and invasive ability of BRCA cancer cells, and tumour xenograft assays have demonstrated the growth-promoting effect of QPRT overexpression in BRCA tumour cells." (PMID 35251175, 2022). "QPRT and DCTPP1 have been reported, but only in a few types of cancers." (PMID 32716908, 2020). "The role of QPRT in BC has not been previously reported; however, its cancer-promoting effects have been observed in other cancers." (PMID 32716908, 2020).
tumor (15 papers, 2014 to 2025). "Further investigation indicated that QPRT was more highly expressed in M2 macrophage cells than in M0 macrophage cells, and the expression of QPRT in two different tumour-associated macrophages was also higher than that in M0 macrophages." (PMID 37723185, 2023). "Neuroendocrine differentiation of tumor cells is associated with down-regulation of genes relevant to quinolinate phosphoribosyltransferase-dependent de novo NAD synthesis, promoting NAMPTi susceptibility in vitro." (PMID 38092728, 2023). "Examination of TCGA dataset of LUAD revealed that SLC7A5 and QPRT are both significantly upregulated in the tumor tissues compared with the normal tissues." (PMID 37095081, 2023). "The formation of QA depends on expression of several enzymes including quinolinate phosphoribosyltransferase (QPRT) activity in tumor cells and 3-hydroxy-anthranilic acid oxygenase (3-HAO), which is normally only expressed in microglial cells." (PMID 33870196, 2021). "It is possible that rosiglitazone and QPRT may also have a similar promoting or inhibitory relationship, thereby influencing the occurrence and development of tumours." (PMID 37723185, 2023). "QPRT is significantly expressed in most tumours, and its expression is related to prognosis." (PMID 35251175, 2022). "Expression of NAMPT, NAPRT, NT5E and QPRT were quantified by qPCR and Western blot in both established and primary GBM cell lines, and IHC was performed on sections from GBM tumours for the same proteins." (PMID 38893173, 2024). "Meanwhile, QPRT might also activate the PI3K-AKT and cell cycle to accelerate tumour growth and survival." (PMID 37723185, 2023). "A tumor xenograft assay demonstrated the tumor-promoting effects of the DCTPP1 and QPRT genes." (PMID 32716908, 2020). "It appears that the majority of tumours down-regulate these latter enzymes to maximise Kyn and KA formation, and while their down-regulation of KYNU and 3-HAAO decreases QA production, QA levels could still be raised by down-regulation of QPRT and ACMSD." (PMID 36286592, 2022).
infection (4 papers, 2016 to 2022). The state of being infected such as from the introduction of a foreign agent such as serum, vaccine, antigenic substance or organism. "Since disruption of QPRT causes lethality in Arabidopsis, QPRT knockdown RNAi lines were generated to assess the effects of a reduced level of QPRT on pathogen infection." (PMID 34445186, 2021). "Up-modulation was specific for NAMPT, while the other three NBEs, i.e., NAPRT, NMRK1, and QPRT, were unaffected by infection with BRAF V600E (heatmaps on the right)." (PMID 35272691, 2022). "Immunoblotting of HCV infected C/OTg livers indicated that QPRT expression was greatly reduced compared to the mock infection." (PMID 28724915, 2017). "As expected, after infection with the avirulent avrRpt2-containing Pst DC3000 strain (Pst-avrRpt2), the QPRT RNAi plants exhibited increased bacterial proliferation compared with Col-0." (PMID 34445186, 2021). "Paralleling trends in the CNS of these animals, we found that upstream enzymes (IDO1, KMO, and KYNU) displayed significant mRNA upregulation during at least one phase of infection, while downstream enzymes (HAAO and QPRT) were either downregulated or unchanged." (PMID 28066416, 2016).
neurodegenerative disease (3 papers, 2015 to 2024). A disorder of the central nervous system characterized by gradual and progressive loss of neural tissue and neurologic function. "QPRT is also essential for maintainingthe homeostasis of quinolinic acid in the brain, a possible neurotoxin causingvarious neurodegenerative diseases." (PMID 26805589, 2016). "The QPRT gene is included in neuronal health by breaking down quinolinate, which could otherwise harm neurons and is associated with neurodegenerative diseases." (PMID 39457550, 2024). "In the context of neuroinflammatory and degenerative diseases, where elevated QUIN contributes to the pathogenesis, increasing expression or activity of QPRT may provide a useful therapeutic strategy." (PMID 26114426, 2015).
QPRT also shares sentences with these, for which no sentence is quoted: invasive breast carcinoma (2 papers); autism (1); bladder cancer (1); breast neoplasm (1); chronic kidney disease (1); colitis (1); epilepsy (1); follicular adenomas (1); Growth Deficiency (1); hepatocellular carcinoma (1); Huntington disease (1); lung adenocarcinoma (1); malignant pheochromocytomas (1); metabolic syndrome (1); mitochondrial disease (1); Mitochondrial myopathy (1); mood disorder (1); neurodevelopmental disorder (1); tuberculosis (1).